HSPB1 (heat shock protein family B (small) member 1)
Diseases named in the same sentence as HSPB1 in open-access papers (continued):
Sharing a sentence is not in itself a finding about the gene and the disease.
cardiomyopathy (7 papers, 2017 to 2022). A disease of the heart muscle or myocardium proper. "Overexpression of HSPB1 conferred protection against myocardial ischemia-reperfusion injury, whereas overexpression of HSPB1 caused reductive stress and cardiomyopathy in another study." (PMID 31323898, 2019). "Fourth, studies have shown that recombinant HSPB8 or HSPB1 can interrupt amyloid formation, thus proving to be a potential therapeutic strategy for treating certain cardiomyopathies." (PMID 35011676, 2021). "In the section of cardiomyopathy, reductive stress-inducing factors including heat shock protein 27 (Hsp27 or HspB1), alpha-B crystalline (CryAB or HspB5), and Nrf2 were specifically elaborated." (PMID 32566086, 2020). "Wild type HSPB1 can also exert anti-apoptotic functions in HeLa cells transfected with mutant HSPB5; these variants elevated cellular apoptosis level and were associated with congenital cataract and cardio-myopathy." (PMID 36291591, 2022). "However, a recent study showed that Hmgb1 can upregulate the expression of Hspb1 and attenuate the cardiomyocyte apoptosis associated with DOX-induced cardiomyopathy." (PMID 33110475, 2020). "Moreover, HSPB1 is co-localized with the titin spring in the elastic I-band region in dialated cardiomyopathy patients, while HSPB1 is mainly expressed in cytoplasm of cardiomyocytes in the healthy heart." (PMID 28484965, 2017).
cervical carcinoma (7 papers, 2017 to 2023). A carcinoma arising from either the exocervical squamous epithelium or the endocervical glandular epithelium. "While inhibition of HSPB1 expression increases the anticancer activity of erastin in cervical cancer." (PMID 35775079, 2022). "However, other research has reported that long-term using of the ferroptosis inducer erastin can promote HSPB1 expression in cervical cancer cells, which reduces lipid ROS and iron accumulation, and thus leads to erastin resistance." (PMID 35775079, 2022). "Additionally, the upregulation of HspB1 was also reported in cervical cancer cells and prostatic cancer cells by treatment with 17-allylamino-demethoxygeldanamycin (17-AAG)." (PMID 32927696, 2020). "Moreover, ferroptosis is uncommon in cervical carcinoma cells highly expressing HSPB1 according to recent reports, suggesting HSPB1 provide protective effects on cancer cells." (PMID 33024562, 2020). "Among the multiple proteins secreted by cervical cancer cells, four upregulated proteins were identified: nucleobindin-1 (NUCB1), carboxypeptidase E (CPE), calreticulin (CALR), and heat-shock protein beta-1 (HSPB1)." (PMID 36992411, 2023).
tauopathy (7 papers, 2019 to 2024). Neurodegenerative disorders involving deposition of abnormal tau protein isoforms (tau proteins) in neurons and glial cells in the brain. "Increased levels of HSPB1 in astrocytes are a common feature in other tauopathies such as progressive supranuclear palsy or corticobasal degeneration." (PMID 38507480, 2024). "Our findings provide proof of concept for HSPB1 as a therapeutic target in AD and other tauopathies." (PMID 38507480, 2024). "NC009-1 has been shown previously to have aggregation-reducing and neuroprotection effects by activating HSPB1 to increase pro-aggregated ΔK280 TauRD solubility and promote neurite outgrowth in tauopathy cell model." (PMID 33196459, 2020). "Both HSPB1 and HSPB5 were shown to colocalize with tau fibrils in tauopathy brains and the amount of HSPB1 and HSPB5 was shown to correlate inversely with the levels of granular tau." (PMID 32323160, 2020). "Our data show that, in AD brain, HSPB1 is predominantly expressed in astrocytes, in line with previous immunohistochemistry studies in AD and other tauopathies, where HSPB1 expression was mostly attributed to glial cells, and with recent single-cell transcriptomic studies in human AD brain." (PMID 38507480, 2024). "Increasing the levels of HSPB1 in the brain extracellular space through strategies to deliver recombinant protein or using astrocyte-directed gene therapy vectors constitutes potential therapeutic avenues in AD and related tauopathies." (PMID 38507480, 2024). "This work identifies a unique mechanism by which HSPB1 is secreted from astrocytes in reactive conditions to mediate autocrine and paracrine neuroprotective functions and highlights the therapeutic potential of HSPB1 to ameliorate tau pathology in AD and related tauopathies." (PMID 38507480, 2024). "Previously, indole compound NC009-1 (C19H16N2O3) has been shown to have aggregation-reducing and neuroprotective effects by activating heat shock protein beta 1 (HSPB1) in tauopathy cell model and spinal spinocerebellar ataxia (SCA) type 17 cell and mouse models." (PMID 36768965, 2023). "Previously, we have shown that indole compound NC009-1 displays aggregation-reducing and neuroprotective effects by activating heat shock protein family B (small) member 1 (HSPB1) in tauopathy cell model and spinocerebellar ataxia type 17 cell and mouse models." (PMID 37578928, 2023). "In mice, overexpression of HSPB1 was found to be partially protective against tauopathy." (PMID 32323160, 2020).
Cerebral ischemia (6 papers, 2012 to 2025). Restriction of arterial blood supply to the brain associated with insufficient oxygenation to support the metabolic requirements of the tissue. "HSPB1 exerts powerful neuroprotective effects, and overexpression of HSPB1 in transgenic animals confers robust cellular protection against a variety of neurological insults and diseases, including cerebral ischemia." (PMID 29662435, 2018). "Intravenous infusion of human-derived HSPB1 or recombinant HSPB1 with a cell-penetrating peptide reduced blood-brain barrier dysfunction and improved neurological deficits, including reduced glia activation in mice following brain ischemia." (PMID 38507480, 2024).
osteosarcoma (6 papers, 2017 to 2024). A usually aggressive malignant bone-forming mesenchymal neoplasm, predominantly affecting adolescents and young adults. "Osteosarcoma/prostate adenocarcinoma: Heat shock protein beta-1 (HSPB1) functions as an inhibitor of ferroptosis in cancer." (PMID 38072908, 2023). "Extensive research currently delves into the potential role of individual HSPs such as HSPB1, HSPBP1, and HSP90AA1 in influencing the survival and advancement of osteosarcoma, yet the prognostic value and molecular mechanisms of other HSP family members in osteosarcoma remain to be elucidated 72-77." (PMID 39430254, 2024).
pancreatic cancer (6 papers, 2016 to 2024). "A previous study showed that HSPB1 was abnormally highly expressed in pancreatic cancer tissues and promoted pancreatic cancer progression." (PMID 38682349, 2024). "In this study, we found that HSPB1 was enriched in pancreatic cancer cell‐derived exosomes and played a promoting role in pancreatic cancer by suppressing ferroptotic cell death." (PMID 38682349, 2024). "In this study, we reported that HSPB1 is enriched in exosomes‐derived pancreatic cancer cells and functions as a proto‐oncogene by suppressing Nrf2/P450‐mediated ferroptosis." (PMID 38682349, 2024). "We found that HSPB1 was enriched in the exosomes derived from human pancreatic cancer cell lines SW1990 and Panc‐1." (PMID 38682349, 2024). "Our study firstly reported the role of the suppressive role of HSPB1 in hypoxic pancreatic cancer cells and also proposed a novel mechanism of HSPB1 in regulating ferroptosis." (PMID 38682349, 2024). "Tumour tissues and matched paracancerous tissues were collected from 30 patients with pancreatic cancer, and RT‐qPCR results indicated that the expression of HSPB1 mRNA in tumour tissues was significantly higher than that in paracancerous tissues." (PMID 38682349, 2024). "Next, Western blotting results confirmed that HSPB1 was abundantly enriched in exosomes derived from human pancreatic cancer cells." (PMID 38682349, 2024). "Here, using datasets from GEO and TCGA, we screened HSPB1, related to the P450 monooxygenase signalling, a fuel of ferroptosis, to be a candidate gene for regulating pancreatic cancer cell ferroptosis." (PMID 38682349, 2024). "Phosphorylation of HSPB1 in S15 and S82 is the most up-regulated event in treatment with chemotherapy in pancreatic cancer, raising the tumour resistance." (PMID 37569364, 2023). "In summary, pancreatic cancer cells secret exosomes containing abundant HSPB1 protein." (PMID 38682349, 2024). "Representative Western blots and IHC images of the specimens showed that HSPB1 protein was also obviously upregulated in the tumour tissue and mainly located in the nucleus Furthermore, the expression of HSPB1 was upregulated in pancreatic cancer cell lines." (PMID 38682349, 2024). "Moreover, the role and mechanism of exosomal HSPB1 in regulating pancreatic cancer cell ferroptosis was investigated in‐depth." (PMID 38682349, 2024). "In conclusion, we screened HSPB1 as an exosomal protein regulator for ferroptosis of pancreatic cancer cells, and exosomal HSPB1 played a promoting role in pancreatic cancer progression by interacting with the RNA binding protein FUS and suppressing FUS/NRF2/HO‐1/P450‐mediated ferroptosis." (PMID 38682349, 2024). "Exosomes enter surrounding pancreatic cancer cells and release the exosomal HSPB1 protein." (PMID 38682349, 2024). "Additionally, clinical trials showed that the binding of RP101 (brivudine) to HSPB1 increases survival in both experimental animals and pancreatic cancer patients." (PMID 34578333, 2021). "Therefore, targeting HSPB1 may be a promising strategy to modulate ferroptosis of pancreatic cancer cells via multiple pathways." (PMID 38682349, 2024). "In conclusion, exosomal HSPB1 interacts with the RNA binding protein FUS and decreases FUS‐mediated stability of Nrf2 mRNA, thus suppressing hypoxia‐induced ferroptosis in pancreatic cancer." (PMID 38682349, 2024). "However, it is not clear whether HSPB1 is enriched in gastrointestinal cancer cell‐derived exosomes and what is the exact role of exosome‐HSPB1 in pancreatic cancer." (PMID 38682349, 2024).
viral infections (6 papers, 2011 to 2024). "HSPB1 synthesis increases in response to a variety of stresses (e.g. elevated temperatures, heavy metals, toxins, oxidants, bacterial and viral infections) in order to minimize the deleterious consequences of these stimuli and provide the maximal cytoprotective effect." (PMID 26719749, 2015). "In contrast, its abundance was found to be decreased in cells infected in vitro with mumps virus and porcine circovirus type 2, which suggests that HSPB1 may play different roles in different virus infections or different stages of infection." (PMID 21385394, 2011). "HSPB1 is an important small heat shock protein (HSP) that is synthesized in response to a wide variety of stressful stimuli, including viral infection." (PMID 21385394, 2011).
heart failure (5 papers, 2012 to 2020). Inability of the heart to pump blood at an adequate rate to meet tissue metabolic requirements. "Similarly, treatment of the CryABR120G mutant mouse model of desmin-related cardiomyopathy with the drug geranylgeranyl-acetone (increasing HSPB8 and HSPB1) significantly reduces heart failure." (PMID 26664897, 2015). "In MLP KO mice, which display heart failure, we detected an interaction between HspB1 and FLNC and prevalent phosphorylation of HspB1 at Ser82." (PMID 31131323, 2019). "We have also summarized the recent discovery of phosphorylation and upregulation of HspB1 in the hearts of a mouse model of heart failure alongside an interaction with FLNC, pointing to a force-dependent mode of strengthened client binding upon HspB1 phosphorylation." (PMID 32253742, 2020).
ischemia (5 papers, 2011 to 2025). A hypoperfusion of the BLOOD through an organ or tissue caused by a PATHOLOGIC CONSTRICTION or obstruction of its BLOOD VESSELS, or an absence of BLOOD CIRCULATION. "Ischemic postconditioning in the kidney reduced the adverse effects of ischemia such as lipid peroxidation, apoptosis, and inflammation by increasing the expression of Hsp70 and Hspb1." (PMID 38681734, 2024). "Previous reports have shown that HSPB1 also has a neuroprotective effect and that HSPB1 overexpression reduces apoptosis induced by ischemia in the liver." (PMID 25962073, 2015). "In stress conditions like ischemia, HSPB1 can enhance myocardial cells' resistance to ischemic injury, indicating that HSPB1 is an important kind of heat shock protein with protective function in myocardial tissues." (PMID 26229544, 2015).
Obesity (5 papers, 2013 to 2025). Accumulation of substantial excess body fat. "To better understand how human HSPB1 influences the progression of MetS, we further investigated the underlying mechanisms of obesity-related complications, including inflammation, NAFLD, and impaired cardiac function and morphology." (PMID 40855499, 2025). "Previous studies in obesity showed a direct association between HSPB1 abundance and BMI, or high levels of HSPB1 and IR, suggesting an important role in metabolic disorders." (PMID 38703299, 2024). "In the present study, we analyzed the effects of human HSPB1 on obesity-related complications and comorbidities by crossing a human HSPB1-overexpressing strain with a mouse model of MetS overexpressing human APOB-100." (PMID 40855499, 2025). "In our present study, another interesting sex-dependent effect of obesity and human HSPB1 overexpression was observed for Fgf21, a peptide hormone involved in energy homeostasis regulation." (PMID 40855499, 2025). "In APOB animals, HSPB1 overexpression exerted a sex-dependent influence on obesity-related alterations, including weight gain, hypercholesterolemia, and hepatic and vWAT gene expression." (PMID 40855499, 2025). "At first sight, the increased weight gain and serum LDL level in the APOB/HSP females suggest that the overexpression of human HSPB1 contributes to the detrimental consequences of obesity." (PMID 40855499, 2025). "Therefore, the present study aimed to investigate the effects of a small heat shock protein, HSPB1, on the comorbidities and complications of obesity in a transgenic mouse model." (PMID 40855499, 2025). "In conclusion, human HSPB1 may be involved in the regulation of obesity-related metabolic alterations; however, it has sex-dependent effects." (PMID 40855499, 2025). "Based on the estrogen-dependent atheroprotective function of extracellular human HSPB1 in previous studies, human HSPB1 may have a complex regulatory role in obesity-related comorbidities." (PMID 40855499, 2025).
schizophrenia (5 papers, 2017 to 2024). A major psychotic disorder characterized by abnormalities in the perception or expression of reality. "Changes in HSPB1 expression levels were observed in patients with schizophrenia, and HSPB1 polymorphisms were associated with an increased risk of schizophrenia." (PMID 37383091, 2023). "However, further investigations in other independent larger samples in different ethnicities are required to confirm our findings and to better explore the effect of the HSPB1 polymorphisms on the risk and symptomatology of schizophrenia." (PMID 35340410, 2022). "In addition, polymorphism of HSPB1 is associated with schizophrenia." (PMID 38664915, 2024).
cardiac ischemia (4 papers, 2018 to 2024). "Previous studies have reported that TLR4 regulates PGC‐1α after myocardial ischemia and that TLR4 abundance is associated with HSPB1 level." (PMID 38420163, 2024). "HSPB1 induces beneficial outcomes in neuroprotection, and overexpression of HSPB1 in transgenic animals confers robust cellular protection against a variety of neurological insults and diseases, including cerebral and cardiac ischemia." (PMID 29662435, 2018). "During cardiac ischemia injury, HSPB1 is S-thiolated and form homooxidized HSPB1." (PMID 34239687, 2021).
COVID-19 (4 papers, 2020 to 2024). A disease caused by infection with severe acute respiratory syndrome coronavirus 2. "From these proteins CRTAC1, IGLV3-1, HRG, HSPB1, LCP1, ITIH3, and APOA2 have all been identified as correlating with COVID-19 in other research, but to our knowledge, the rest are novel." (PMID 37308820, 2023). "Regardless of the tissue type, we saw consistent increases in genes such as B2M, CD81, GNAS, HLA.B, HSPA1A, HSPB1, and SERPING1 in COVID-19 lungs." (PMID 35233546, 2022).
distal myopathy (4 papers, 2016 to 2025). Distal myopathy refers to a group of muscle diseases which share the clinical pattern of predominant weakness and atrophy beginning in the feet and/or hands. "Recently, distal myopathy had been described in a patient carrying HSPB1 mutation adding to the complexity of phenotypes resulting from HSPB1 mutations." (PMID 28828227, 2017). "In addition, abnormalities of some HSPB members are involved in muscle disorders: HSPB5 mutations are associated with myofibrillar myopathies and HSPB1 or HSPB8 to distal myopathy and Charcot–Mary–Tooth disease type 2." (PMID 29316663, 2018).
epilepsy (4 papers, 2021 to 2025). A brain disorder characterized by episodes of abnormally increased neuronal discharge resulting in transient episodes of sensory or motor neurological dysfunction, or psychic dysfunction. "P2RX plays a significant role in epilepsy-related mitophagy regulation by fine-tuning HSPB1 expression." (PMID 41469519, 2025). "The immune response of HSPB1 was also found to be present in the temporal cortex of patients with epilepsy and was mainly confined to vascular walls and glial cells." (PMID 37735671, 2023).
Insulin resistance (4 papers, 2013 to 2023). Increased resistance towards insulin, that is, diminished effectiveness of insulin in reducing blood glucose levels. "Induction of heat shock proteins may combat insulin resistance, and elevated serum HspB1 levels were also reported in patients with diabetic polyneuropathy." (PMID 29381233, 2018).
leukemia (4 papers, 2015 to 2023). A malignant (clonal) hematologic disorder, involving hematopoietic stem cells and characterized by the presence of primitive or atypical myeloid or lymphoid cells in the bone marrow and the blood. "When JMJD3 is knocked out in human leukemia monocytes (THP-1) cells, the expression of key inflammation markers, such as heat shock protein β-1 (HspB1), increased triple motif protein (TRIM5), and glutathione Glycine peroxidase (Gpx), is dramatically decreased." (PMID 36874364, 2023). "HSPB1/HSP27 is a human small heat shock protein, a chaperone that regulates fundamental cellular processes in normal unstressed cells as well as in many cancer cells, including breast, ovarian, endometrial cancers, osteosarcoma, and leukemia." (PMID 26108672, 2015).
neuroblastoma (4 papers, 2017 to 2024). Neuroblastoma (NB) is the most common solid, extracranial childhood tumor. "To study the pathogenicity of HSPB1‐T139M mutation, we first evaluated the impact of this novel mutation on the overall biological fitness of this stable neuroblastoma cells using MTS cell viability assay (Cory, Owen, Barltrop, & Cory, 1991)." (PMID 28828227, 2017). "Recently, some studies revealed that HSPB1 is enriched in the exosomes derived from multiple cell types associated with or eroded by inflammation, such as cerebral astrocytes, monocytes/macrophages and neuroblastoma cells." (PMID 38682349, 2024). "In addition, we assessed the expression of PCBP1 in differentiated neuroblastoma cell lines expressing either wild type or mutant HSPB1 (P182L or R127W)." (PMID 28077174, 2017).